TGFB1 (transforming growth factor beta 1)
Diseases named in the same sentence as TGFB1 in open-access papers (continued):
Sharing a sentence is not in itself a finding about the gene and the disease.
asthma (575 papers, 2005 to 2026). "In particular, T allele of the −509C/T and C allele of the +869T/C polymorphisms in TGFB1 were shown to strongly associate with the risk of asthma development." (PMID 39949968, 2025). "As higher TGFβ1 levels correlate with more severe asthma symptoms, it is plausible that individuals carrying the rs2241715 C allele exhibit higher TGFβ1 levels." (PMID 38970443, 2024). "Among many suggested GMs, a validated GM is a variant in the TGFβ1 gene, well-known for its inflammatory and remodeling role, thus exerting an effect on asthma and chronic obstructive pulmonary disease." (PMID 37761826, 2023). "Transforming growth factor-beta 1 (TGFβ1), a major mediator of airway remodeling is linked with asthma severity." (PMID 37932719, 2023). "GL also exhibited an anti-inflammatory effect against asthma by modulating the TGFβ1-Smad signaling pathway in asthma-associated airway inflammation mice model, and then remodeled the airway." (PMID 36313350, 2022). "Inhibition of RhoA suppressed BaP and Der f 1 co-exposure-induced airway hyper-responsiveness, Th2-associated airway inflammation, and TGFβ1 signaling activation in asthma." (PMID 33936062, 2021). "Single Nucleotide Polymorphism (SNP) rs8179181 in the TGFβ1 gene induces childhood asthma and atopy development." (PMID 34620181, 2021). "A variant in the promoter region (C-509T), thought to be associated with increased TGFβ1 expression, was studied as a potential contributor to asthma disease severity." (PMID 23630497, 2013). "Gasdermin-family proteins have been implicated in TGFβ1 signalling and epithelial cell apoptosis, with increased airway cell apoptosis reported in severe asthma." (PMID 24066901, 2013). "Several genetic studies have associated some of the common single nucleotide polymorphisms (SNP) found in the TGFB1 gene or its promoter with asthma phenotypes, supporting its potential role in the pathogenesis of this disease." (PMID 17892594, 2007). "Expression of isoforms of TGFβ 1 - 3 cytokines is influenced by tagging single nucleotide polymorphisms (SNPs) in the TGFβ1, TGFβ2 and TGFβ3 genes, which may be associated with asthma and other diseases." (PMID 35774789, 2022). "Moreover, except for ATG3, HDAC1, and TGFB1, correlation analysis showed that the expression of the aging-related genes in peripheral blood of asthma patients was associated with pulmonary function parameters (FEV1%, FEV1, FVC, PEF, FEF75, FEF50, and FEF25)." (PMID 34136532, 2021). "Expression of isoforms 1–3 of TGFβ cytokine is influenced by tagging polymorphisms in the TGFβ1, TGFβ2 and TGFβ3 gene, and these SNPs may be associated with the risk of asthma development and severity as well as with other diseases." (PMID 34620181, 2021). "A meta-analysis further suggested that C509T or T869C polymorphism of TGFB1 gene may predispose to asthma." (PMID 30127261, 2018). "Since asthma has been strongly associated with increased expression of TGFβ1 in the airway, epithelial to mesenchymal transition may contribute to the contractile and fibrotic remodeling process that accompanies chronic asthma." (PMID 19857272, 2009). "TGFβ1 is a pro-fibrotic cytokine that has been implicated in airway remodelling in asthma and therefore it is tempting to speculate that TGFβ1 induction of uPAR may be a significant mechanism involved in airway remodelling." (PMID 19638192, 2009). "Importantly, we made novel findings that BaP-activated AhR can bind to the promoter region of RhoA and regulate RhoA/Rho-kinase activation, and inhibition of RhoA significantly suppresses co-exposure-induced AHR, Th2-associated airway inflammation, and TGFβ1 signaling in a mouse model of asthma." (PMID 33936062, 2021). "This study reported that integrin α5 (ITGA5) was markedly upregulated in asthma patients, house dust mite (HDM)-sensitised asthma mice, and transforming growth factor beta 1 (TGF-β1)-induced in vitro EMT models." (PMID 41772919, 2026).
asthma (continued). "Common variants in TGFB1, PDGFRA, and ECM-related genes have been linked to asthma severity, airway wall remodeling, and reduced lung function." (PMID 41279414, 2025). "The interaction of cytokines such as interleukin (IL)-4, transforming growth factor-beta 1 (TGF-β1), tumor necrosis factor-alpha (TNF-α), and IL-17 are also implicated in asthma pathogenesis." (PMID 38731707, 2024). "These include inflammatory cytokines IL4 (z = 0.096, p = 7.25 × 10−10) and TGFβ1 (z = −1.711, p = 5.47 × 10−8), both of which are known to play key roles in asthma." (PMID 38806494, 2024). "There is significant literature associating genetic/epigenetic variations in TGFB1 and its downstream signalling pathway (SMAD3) to asthma and atopy and heightened susceptibility of allergic disease." (PMID 37438758, 2023). "Chitinases modulate TGFβ1 inflammatory and tissue remodeling activities which correlate with asthma severity and fibrotic processes development." (PMID 36902148, 2023). "OATD-01 in a dose-dependent manner inhibited active TGFβ1 release, a macrophage-derived cytokine and a known driver of subepithelial fibrosis in asthma." (PMID 36902148, 2023). "Results showed that TGFβ1 and p-Smad3 expression substantially increased in the airways of mice with acute asthma induced by OVA compared with normal mice." (PMID 34671356, 2021). "Collectively, our studies identified a functional axis of AhR–RhoA that regulates the activation of TGFβ1/Smad3 signaling, thereby leading to the development of allergic airway inflammation and asthma." (PMID 33936062, 2021). "TGFβ1, a pleiotropic fibrogenic and immunomodulatory factor, is involved in asthma, both in the airway inflammatory response and in the fibrotic remodeling." (PMID 33925009, 2021). "We found that BaP co-exposure potentiated Der f 1-induced TGFβ1 secretion and signaling activation in human bronchial epithelial cells (HBECs) and the airways of asthma mouse model." (PMID 33936062, 2021). "Among such loci identified by GWAS, chromosome 19q13 that carries genes, including TGFB1, B9D2 and TMEM91, has been reported to harbor multiple single-nucleotide polymorphisms (SNPs) that are linked to asthma, CF and/or COPD." (PMID 32500120, 2020). "Here, we demonstrate that NOX4 integrates TGFβ1 and mechanical signaling in fibroblast differentiation and lung remodeling during asthma." (PMID 32555397, 2020). "In this modest number of genes identified several have been previously associated with airway biology and disease including e.g. TGFBR1, the receptor for TGFB1 involved in fibrosis and IL6R a cytokine receptor implicated in airway disease e.g. asthma." (PMID 31370853, 2019). "Expression levels of TSLP, the master-regulator of airway remodeling during asthma, and of TGFβ1, which is involved in airway inflammation and hyper-responsiveness, were also decreased in IL-6 KO mice as compared to WT mice." (PMID 30534125, 2018). "The role of EMT in the development of subepthelial fibrosis, has been considered upon observation of elevated TGFβ1 production by eosinophils and fibroblasts in patients with severe and moderate asthma." (PMID 24982697, 2014). "In conclusion, future studies aiming at defining asthma endotypes should consider identification of mechanisms and respective biomarkers of TGFβ1 mediated EMT." (PMID 24982697, 2014). "In the airway of asthma patients, TGFβ1 is known to activate p38 MAPK–signaling pathway which initiates apoptosis." (PMID 23460857, 2013). "Interest in investigating TGFβ1 as a potential modifier of CF pulmonary disease stemmed from both its biologic plausibility, and its identification as a modifier of asthma and chronic obstructive pulmonary disease (COPD)." (PMID 23630497, 2013). "Although, the regulation of TGFβ1 in asthma remains incompletely understood, many investigators have reported increased TGFβ1 levels in asthma." (PMID 19857272, 2009).
asthma (continued). "TGFβ1 is known to be expressed by a variety of inflammatory and structural lung cells in asthma, and is also recognized to be involved in lung fibrosis." (PMID 19857272, 2009). "It equally raises the possibility that the baseline overexpression of TGFβ1 observed in asthma by certain investigators is related to the increased production of this cytokine by alveolar macrophages." (PMID 17892594, 2007). "The first purpose of the current work is to review the published data concerning the expression of TGFβ1 in asthma and to discuss the cellular sources to this cytokine in this particular disease." (PMID 17892594, 2007). "Together, these observations raise doubts on the techniques currently used to measure the expression of different mediators in the airways and, for instance, the increased expression of TGFβ1 in asthma." (PMID 17892594, 2007). "Since the TGFβ2 isoform acts on the same receptors and signal via the same AR-Smads as TGFβ1, these results indicate that TGFβ2 is also a likely candidate to explain activation of Smad signaling in asthma." (PMID 17892594, 2007). "If this conjecture is true, and because asthma is an inflammatory condition of the airways, it is expected that TGFβ1 would be upregulated in asthmatic airways at a later time-point following challenge." (PMID 17892594, 2007). "On the other hand, it is becoming clear that TGFβ1 signaling is increased in the lungs of asthmatics, which testifies the increased activity of this cytokine in asthma pathogenesis." (PMID 17892594, 2007). "In a transgenic model of asthma induced by lung overexpression of IL-13, TGFβ1 mRNA and protein were observed mainly in macrophages, but also in type II pneumocytes, airway epithelial cells and occasionally in eosinophils." (PMID 17892594, 2007). "In support of the inflammatory role of TGFβ1 in asthma, others have shown that its release by structural cells in the airways contributes to inflammatory cell recruitment." (PMID 17892594, 2007). "In asthma, the cellular origin of TGFβ1 is less clear and numerous inflammatory cells as well as structural cells were shown to contribute." (PMID 17892594, 2007). "Notably, the TGFB1 promoter polymorphism C-509T (rs1800469) in humans has been linked to increased TGFB1 transcription and heightened AHR and asthma severity." (PMID 41279414, 2025). "Chronic environmental exposure to gaseous pollutants, such as NO2 and O3, may upregulate the expression of certain genes, such as TGFB1, in the eosinophils of patients with asthma." (PMID 39575691, 2024). "For example, transforming growth factor-beta 1 (TGF-β1) may induce EMT in asthma, and it was shown to be increased in the bronchoalveolar lavage fluid of patients with asthma and was associated with increased airway thickness." (PMID 38074219, 2023). "It should be pointed out here that it has not been well documented that this rs8109627 in the TGFβ1 gene plays a role in increasing the risk of asthma." (PMID 34620181, 2021). "In addition, we detected TGFβ1 in the airway epithelial cells of an asthma mouse model by co-immunofluorescent staining TGFβ1 with epithelial cell marker EpCAM." (PMID 33936062, 2021). "Here we demonstrated that TGFβ1 was increased not only in supernatants (soluble TGFβ1) of BaP/Der f 1-treated human airway epithelial cells but also in airway epithelial cells (membrane-bound form) of a BaP/Der f 1-treated mouse model of asthma." (PMID 33936062, 2021). "Importantly, several studies including ours have suggested a feed-forward circuit between RhoA signaling and TGFβ1 that drives airway constriction, airway hyper-responsiveness, and airway remodeling in asthma." (PMID 33936062, 2021). "Our purpose was to determine whether genotypes of MAC/SNP TGFβ1, TGFβ2, and TGFβ3 are related to the level of asthma control, measured with the application of the Asthma Control Test (ACTTM) in asthmatics and healthy controls." (PMID 34620181, 2021).
asthma (continued). "Similarly, the severe, late-onset eosinophilic asthma endotype, representing 20% of the severe asthma population, also shows features of TGFβ1 mediated EMT and airway remodeling in spite of good response to systemic corticosteroid therapy." (PMID 24982697, 2014). "In patients with severe asthma, eosinophils constitute the majority of TGFβ1 producing cells as bronchial biopsies showed that 65% of TGFβ1 mRNA-positive cells are eosinophils and 75% of lung eosinophils were positive for TGFβ1 mRNA." (PMID 24982697, 2014). "Studies have also suggested a role for TGFβ-1 in airway remodelling in asthma in animal models." (PMID 23717571, 2013). "Variation in TGFβ1 has been shown to modify asthma and COPD." (PMID 23630497, 2013). "We hypothesized that exposure of normal bronchial epithelial cells to chronic TGFβ1 stimulation would cause them to undergo EMT, potentially representing another source of myofibroblasts involved in airway remodeling in asthma." (PMID 19857272, 2009). "Therefore, upregulation of asthma mediators, such as TGFβ1, is also likely to be inducible and transient in nature." (PMID 17892594, 2007). "With all data taken together, one might imagine the following scenario of TGFβ1 regulation in asthma and its potential role in the pathogenesis of the disease." (PMID 17892594, 2007). "Hence, in addition to looking at the right time, investigators attempting to document an increased expression of TGFβ1 in asthma need to look at the right place." (PMID 17892594, 2007). "Even if TGFβ1 upregulation in asthma is considered as a dogma by certain investigators in the field, the overall picture of the published litterature is not that clear and the cellular origin of this cytokine in the airways of asthmatics is still a contemporaneous debate." (PMID 17892594, 2007). "Collectively, these studies suggest that macrophages are a likely source of TGFβ1 in asthma." (PMID 17892594, 2007). "However, antibody to TGFβ1 was shown to prevent phosphorylation of Smad2 in a murine model of prolonged allergen challenge-induced asthma." (PMID 17892594, 2007). "Consequently, in the case of severe asthma where neutrophils predominate, neutrophils would be the main source of TGFβ1; and in the case of mild to moderate asthma where eosinophils predominate, eosinophils would be the principal cells secreting this cytokine." (PMID 17892594, 2007). "It is known that TGFβ1 is widely expressed throughout the body and that every resident structural and immune cell in the lung, as well as every inflammatory cell mobilised to the airways during asthma exacerbation, is able to express and secrete TGFβ1." (PMID 17892594, 2007). "Determining the sequence and the kinetics of TGFβ1 expression may be important to increase our understanding of the role of this cytokine in asthma." (PMID 17892594, 2007). "The potential role for TGFβ1 in asthma pathogenesis has also been reviewed recently." (PMID 17892594, 2007). "TGFβ1 signaling is mediated intracellularly via the phosphorylation and subsequent nuclear translocation of SMAD2/3 transcription factors, and both genome-wide association and epigenetic studies have identified associations between components of the TGFβ1 signalling pathway and asthma risk." (PMID 34367159, 2021). "The correlation of airway remodeling with features of EMT, expression of TGFβ1, severity of disease, resistance to glucocorticoid therapy and airway eosinophilia or neutrophilia can be used to define distinct molecular phenotypes of asthma and to some degree asthma endotype." (PMID 24982697, 2014). "The teleologic advantage of an increased TGFβ1 production by these cells in asthma is unknown." (PMID 17892594, 2007). "Additionally, an in vitro asthma study indicated that cyclopamine and GANT61 alleviated the TGFβ1-induced increase in COL1A1 expression, implying that the activation of Hh signaling in asthma is caused, at least in part, by TGF-β, resulting in the airway remodeling." (PMID 39766192, 2024).
asthma (continued). "In this study, the relationship of this molecule with the regulation of the expression of genes involved in the development of asthma, including MAPK and TGF-β (transforming growth factor beta 1), was confirmed by bioinformatics analysis." (PMID 37511254, 2023). "In asthma, AT2 cells protect the lungs against allergen-induced airway inflammation by secreting TGFβ1, which stimulates regulatory T cell (Treg) development." (PMID 37932719, 2023). "Airway epithelial cells are a major source of pulmonary TGFβ1, and activation of TGFβ1 signaling is essential in allergen-induced exacerbation of AHR and airway inflammation in asthma." (PMID 33936062, 2021). "CLCA1 is also one of the 6 genes (CLCA1, IL4, IL13, MMP12, TGFB1, TLR4) found in common between our KE genesets and the genesets proposed by Bosse24 for COPD and Poole27 for asthma." (PMID 33731770, 2021). "It is known that TGFB1 was a key cytokine that directs airway remodeling, and HDAC1 played a critical role in the pathogenesis of asthma." (PMID 34136532, 2021). "Airway epithelial cells are one of the major sources of TGFβ1, and activation of TGFβ1 signaling plays an important role in the allergen-induced AHR and airway inflammation in asthma." (PMID 33936062, 2021). "In this study, we demonstrated that mechanosensitive ion channel TRPV4 integrates growth factor (TGFβ1) and redox (NOX4) signaling during lung fibroblast differentiation and airway remodeling in asthma." (PMID 32555397, 2020). "Our findings suggest that TRPV4 integrates TGFβ1 and ROS signaling through NOX4 and, TRPV4-NOX4 interaction is amenable to target lung remodeling during asthma." (PMID 32555397, 2020). "Therefore, inconsistencies surrounding the cellular source of TGFβ1 expression in asthma may be related to either the heterogeneity of the asthma groups studied or to the particular states of the disease (exacerbation vs remission period) when the biopsies were taken." (PMID 17892594, 2007). "They demonstrated that during asthma exacerbation, %FEV1 decreased from 86.5 to 51.0% and that TGFβ1 positive cells rose from 1.9 to 55.4% during the same time period." (PMID 17892594, 2007). "A previous study showed that MAP3K19, a component of the MAPK pathway, suppressed allergic airway inflammation in asthma models by modulating epithelial response to stimuli such as TWEAK and TGFβ1, thereby reducing the production of pro-inflammatory cytokines such as RANTES (CCL5)." (PMID 40598285, 2025). "Transforming growth factor-beta 1 (TGFB1), a critical regulator of tissue remodeling and inflammation, plays a well-established role in airway fibrosis and remodeling and impaired alveolarization in BPD, asthma, and COPD." (PMID 40868449, 2025). "The expression levels of IL17RA, IL4RA, integrin β2, CCR3, FCER1A, TGFB1, TLR‐3, TLR‐7, and TLR‐9 in eosinophils treated with IL‐17 for 3 h were higher for normal individuals than for patients with asthma." (PMID 39575691, 2024). "Their functions and effects on the expression of TGFβ1, TGFβ2 and TGFβ3 mRNA, as well as a new pool not yet studied in asthma, had been known before." (PMID 35774789, 2022). "Wnt5a, a prototype of a non-canonical Wnt signaling axis with known cross talk with TGFβ1 during repair and remodeling, was elevated in the airway epithelium of Th17 asthma patients and steroid-resistant asthma." (PMID 33791298, 2021). "The role of rs8109627 in the TGFβ1 gene has not been explicitly and precisely described in the etiopathogenesis of asthma." (PMID 34620181, 2021). "There is increasing evidence to demonstrate that TGFβ1 is one of the major immune-regulatory cytokines from airway epithelial cells that recruit various immune cells to the airways and interact with them to regulate AHR and airway inflammation in asthma." (PMID 33936062, 2021).